CXCL10 (C-X-C motif chemokine ligand 10)
Diseases named in the same sentence as CXCL10 in open-access papers (continued):
Sharing a sentence is not in itself a finding about the gene and the disease.
gastric cancer (continued). "EVs from gastric cancer(GC) cells treated with MLT promote the expression of TNF-α and CXCL10 in macrophages while suppressing IL-6 and MCP-1 expression, concurrently downregulating PD-L1 protein levels." (PMID 38087360, 2023). "Similarly, gastric cancer (GC)-derived exosomal BGN is internalized by macrophages, where it interacts with NONO protein to drive pro-tumoral polarization and CXCL10 upregulation." (PMID 41417432, 2025).
Hypertension (30 papers, 2015 to 2026). The presence of chronic increased pressure in the systemic arterial system. "CXCL10 induces infiltration of T cells in the kidney, causing T cell-driven inflammation and exacerbating hypertension and kidney damage." (PMID 35668739, 2021). "On further analysis adjusting for hypertension and hypercholesterolemia, both the association between CXCL10 and Pattern Recognition Memory in the overall cohort (β:−3.81, SE: 1.61, p = 0.02, Std." (PMID 33424582, 2020). "Serum CXCL10 levels have been found to be significantly higher in patients with high blood pressure and those suffering from essential hypertension." (PMID 35794867, 2022). "Monocyte recruitment is the key factor in the development of vascular inflammation, followed by adhesion molecules (VCAM-1 and ICAM-1), inflammatory factors (TNF-α and IL-6), and chemokines (CCL2, CXCL5, CXCL8, and CXCL10) released during hypertension." (PMID 34335249, 2021). "Prior studies have identified type 2 diabetes to have a significant CXCL10-mediated component and have identified endothelial cell-produced CXCL10 as a contributor to essential hypertension." (PMID 31013714, 2019). "In addition, CXCL10 elevation is also observed in pre-eclampsia and hypertension in pregnancy, which can result in a range of foetal injuries including intrauterine growth retardation and neurological damage induced by hypoxia." (PMID 29768624, 2018). "Stimulated by hypertension, the tissue may secrete various inflammatory factors, including CXCL10." (PMID 35668739, 2021). "Peripheral blood T cells from the miR-214−/− mice infused with Ang II exhibited reduced chemotaxis towards key chemokines involved in hypertension—CCL5 (C-C motif chemokine ligand 5) and CXCL10 when compared with WT mice." (PMID 32065054, 2020). "Comorbidities/risks such as chronic heart disease and hypertension also increased CXCL10 levels and none of the treatments were effective in reducing its levels to baseline." (PMID 37998327, 2023). "This increase in resident cardiac macrophages following renal impairment was dependent upon CXCL10 signalling, but independent of hypertension or renal dysfunction." (PMID 35090403, 2022). "Chemokines also take part in the pathogenesis of hypertension, including monocyte chemoattractant protein-1 (MCP-1, CCL2), Gro-α (growth-related oncogene), interferon-inducible protein (IP-10, CXCL10) interleukin-8 (IL-8; CXCL8), CXCL1/RaNTeS (CCL5)/CCR5 and fractalkine (FKN aka CX3CL1)/CX3CR1." (PMID 32848763, 2020). "Strikingly, what we found in the present study is that there is a significant number of patients with traditionally non-immune kidney diseases, such as hypertension and type 2 diabetes, that had elevated CXCL10, potentially indicating a broader utility in the detection of early-stage kidney injury." (PMID 31013714, 2019).
sarcoidosis (30 papers, 2005 to 2025). Sarcoidosis is a multisystemic disorder of unknown cause characterized by the formation of immune granulomas in involved organs. "Changes in serum CXCL10 levels over time correlated with both chronic progressive disease (associated with sustained elevations of CXCL10) or remitting sarcoidosis (associated with a reduction over time in CXCL10)." (PMID 24199653, 2013). "Control subjects exhibit higher CXCL10 levels than IPF patients in tissue specimens, while sarcoidosis patients have higher BALF CXCL10 levels than IPF patients." (PMID 39768150, 2024). "In an independent subgroup of CVID patients, sarcoidosis patients as well as healthy donors we performed an analysis by MultiPlex Bead Arrays of BAL fluids for CXCL10, IL-4, IL-10, IL-12, and IL-17." (PMID 33613543, 2020). "DEX treatment decreased expression of numerous cytokine and chemokine genes in sarcoidosis monocytes, while increasing the expression of CXCL10 and IL-10." (PMID 32477331, 2020). "Similar to sarcoidosis CXCL10 is significantly elevated in CVID-ILD derived BALF being one of the main chemokines attracting not only CXCR3 positive TH1 cells but also CD21lowT-bethi B cells which likewise express high levels of this chemokine receptor." (PMID 33613543, 2020). "We found that CXCL9 and CXCL10 were indeed elevated in the serum of sarcoidosis subjects compared to controls and further, found that their levels correlated with the lung function measurements DLCO and FVC, respectively." (PMID 24199653, 2013). "The mean increase in serum CXCL10 in chronic sarcoidosis was 4.3 ± 14 pg/ml, compared to a drop of 12.8 ± 11 pg/ml in the remitting sarcoidosis group, p = 0.002." (PMID 24199653, 2013). "We found statistically significant increases in CXCL9, CXCL10, and sIL2R in sarcoidosis subjects compared to control subjects." (PMID 24199653, 2013). "Serum levels of CXCL9, CXCL10, and proteins associated with inflammation and/or disease activity (sIL2R, ACE, ESR and CRP) were measured in a prospective cohort of sarcoidosis subjects and controls." (PMID 24199653, 2013). "In the longitudinal analysis, subjects with chronic sarcoidosis were significantly more likely to show persistent elevations in CXCL10, whereas those with remitting sarcoidosis had declines in CXCL10 over time." (PMID 24199653, 2013). "The concentrations of ACE, CRP, ESR, CXL9, CXCL10, and sIL2R were all significantly elevated in sarcoidosis subjects when compared to control subjects." (PMID 24199653, 2013). "In the longitudinal measurements, the majority of subjects with chronic sarcoidosis demonstrated persistently elevated or increased serum CXCL10 levels, whereas remitting sarcoidosis subjects consistently showed a decrease in serum CXCL10." (PMID 24199653, 2013). "In summary, we found that serum CXCL9 and CXCL10 levels correlated with sarcoidosis disease severity as assessed by FVC and DLCO, as well as the Wasfi severity score, which incorporates additional clinical phenotypes of sarcoidosis." (PMID 24199653, 2013). "Interferon-γ–inducible chemokines, CXCL9 and CXCL10, are elevated in sarcoidosis and inter-correlated with each other." (PMID 24199653, 2013). "We also found that CXCL10 remained elevated among chronic sarcoidosis subjects compared to healthy controls despite immunosuppression use." (PMID 24199653, 2013). "We previously identified up-regulated transcripts for interferon-inducible chemokines CXCL9, and CXCL10, in blood of sarcoidosis patients compared to controls." (PMID 24199653, 2013). "We and other authors have previously shown that CXCR3/CXCL10 interaction is involved in the pathogenesis of other Th1-mediated processes, such as Crohn's disease and sarcoidosis." (PMID 15743470, 2005). "CXCL10 was also increased in most of the sarcoidosis patients." (PMID 33613543, 2020).
sarcoidosis (continued). "Our findings in the peripheral blood, along with data from several other cross-sectional BALF studies, suggest that CXCL9 and CXCL10 may play important roles in the pathogenesis of sarcoidosis." (PMID 24199653, 2013). "Induction of CXCR3 with CXCL9 and/or CXCL10 allows for T cell migration into organ tissues, including those that are typically thought of as immune privileged, and contributes to Th1 cell differentiation, which are common features of sarcoidosis." (PMID 24199653, 2013). "Similarly, our prior whole blood gene expression data from sarcoidosis and control subjects confirmed that transcripts for CXCL10 were significantly more upregulated compared to CXCL9 in sarcoidosis (Gene Expression Omnibus, GSE19314)." (PMID 24199653, 2013). "Notably CXCL10 is strongly expressed in sarcoidosis tissues." (PMID 24199653, 2013). "Furthermore, a number of studies have measured CXCL10 in BALF from sarcoidosis patients." (PMID 24199653, 2013). "It is worth mentioning that in the BALF derived from patients with sarcoidosis, an increase of ligands for CXCR3 and CCR6 (e.g., CXCL10 and CCL20, respectively) is seen." (PMID 41376646, 2025). "For example, CD103+CD4+ T-cells in BALF of sarcoidosis patients are lower than in other ILD, while some chemokines able to recruit T-helper lymphocytes, such as CXCL9, CXCL10, and CXCL11, are increased." (PMID 39062076, 2024). "When comparing the entire sarcoidosis cohort with the healthy cohort, the values for all markers (SAA, CCL18, CA15.3, CXCL9, CXCL10, and CTO) statistically significantly differ (p-values ≤ 0.001), except for SP-D (p-value = 0.23)." (PMID 37445972, 2023). "Patients with ground-glass lesions are a seemingly biochemically specific subgroup of intrathoracic sarcoidosis, with increased levels of SAA, CXCL9, CXCL10, CCL18, CTO, and CA15.3." (PMID 37445972, 2023). "Moving on to biomarker analysis, our sarcoidosis cohort displays statistically significantly increased levels of granulomatous disease markers CXCL9 and CXCL10." (PMID 37445972, 2023). "IL18R1 was highly expressed in severe viral and bacterial LRTI and SIRS, whereas CXCL10 was highly expressed in severe viral LRTI and in one of the sarcoidosis studies." (PMID 36561889, 2022). "IP-10 (also called CXCL10), which was removed due to its high expression in severe viral LRTs and sarcoidosis, appears in several proteomic studies." (PMID 36561889, 2022). "In contrast to our negative findings regarding macrophage polarization, previous studies have demonstrated higher expression of the M1 markers CXCL10, CXCL11 and CXCL16 in sarcoidosis patients compared to healthy subjects." (PMID 20813038, 2010). "Compared to healthy donors, subjects with sarcoidosis had significantly higher levels of circulating IL-18, CXCL10, sIL-2R/CD25 and TNFR II, but not other tested cytokines." (PMID 38173720, 2023). "All our sarcoidosis patients had increased serum concentrations of CXCL9, CXCL10, CTO, and CCL18." (PMID 37445972, 2023). "Enriched genes including MPO (myeloperoxidase), CXCL11, IL1A, CXCL10, FCGR3B, IL1B, TTN (titin), BATF2, VIP (vasoactive intestinal peptide), TLR3, CCR2, TLR7, and CR1 wereclosely related to sarcoidosis." (PMID 38137330, 2023). "It has been reported that alveolar macrophages from sarcoidosis patients secreted large amounts of CXCR3 ligands, including CXCL9, CXCL10, and CXCL11, that could play crucial roles in the accumulation of Tregs in the site of inflammation." (PMID 37189479, 2023). "When comparing to control subjects, the expression levels of CC chemokines CCL3 (P = 0.043), CCL4 (P = 0.034), CCL5 (P < 0.001), and CCL8 (P = 0.031) and CXC chemokines CXCL9 (P < 0.001), CXCL10 (P = 0.002), and CXCL11 (P = 0.008) were found to be elevated in sarcoidosis patients." (PMID 26696750, 2015). "CXCL10 and CXCL9 significantly correlated with sarcoidosis severity score." (PMID 24199653, 2013).
sarcoidosis (continued). "Thus, individual sarcoidosis patients with higher circulating levels of CXCL10 compared to CXCL9 may have greater activation of the Type I and II interferon pathways, which we speculate could identify subsets of sarcoidosis phenotypes." (PMID 24199653, 2013). "In a cross-sectional analysis of 36 non-immunosuppressed sarcoidosis subjects, serum CXCL9, CXCL10, and sIL2R were significantly elevated compared to 46 controls (p < 0.0001)." (PMID 24199653, 2013).
lymphopenia (29 papers, 2012 to 2025). Reduction in the number of lymphocytes. "Increased levels of CXCL10 decrease T cell proliferation and lead to lymphopenia, which can lead to more severe viral disease." (PMID 39551823, 2024). "We found a significant increase in plasma CXCL9 and CXCL10 at the peak of infection, which coincided with profound lymphopenia." (PMID 37616070, 2023). "Disease severity was associated with changes in innate monocytes and neutrophils, lymphopenia, disrupted cytokine production (increased IL-8 and IP-10/CXCL10 but reduced IFNλ2/3 and IFNγ), and increased endothelial injury (myoglobin, VCAM-1)." (PMID 37598150, 2023). "The propensity of CD4 T cells to die is positively correlated with T cell lymphopenia and higher levels of CXCL10, both markers of disease severity." (PMID 35066575, 2022). "Additionally, CXCL10 and CCL2 were highly expressed in patients with SASR-CoV infection, especially their upregulation expressions can inhibit the development of hematopoietic precursor cells and cause lymphopenia in patients infected with SASR-CoV." (PMID 37087411, 2023). "Moreover, up-regulation of proapoptotic proteins (B-cell lymphoma-2 protein-BCL-2, C-X-C motif chemokine ligand 10- CXCL10, and C-C motif chemokine ligand 2- CCL2) as well as interleukin 6 (IL-6) were presented as molecular alterations associated with lymphopenia in patients with this infection." (PMID 37046564, 2023). "On the other hand, lymphopenia observed in the infected hamsters strongly correlated with the increased levels of IL-1β, IFN-γ, CXCL10, and CCL2, indicating a dysregulation of T-helper-1 (Th1) cell function." (PMID 36618412, 2022). "The release of chemokines such as CXCL-10/IP-10 and CCL-2/MCP-1 may also contribute to CD4 lymphopenia, mostly due to the suppression of hematopoietic progenitor cells proliferation, or to the inhibition of IL-2 signaling pathway." (PMID 34122423, 2021). "CXCL-10/IP-10 and CCL-2/MCP-1 could suppress haematopoietic progenitor cells proliferation, ultimately leading to lymphopenia." (PMID 32922406, 2020).
Alzheimer disease (28 papers, 2011 to 2025). A progressive, neurodegenerative disease characterized by loss of function and death of nerve cells in several areas of the brain leading to loss of cognitive function such as memory and language. "Previous studies reported elevated levels of the antimicrobial chemokine IP-10 (CXCL10) associated with neuroinflammation and cognitive impairment reported in Alzheimer’s disease and dementia." (PMID 36981618, 2023). "In Alzheimer’s patients, while CXCR3 expression level remained unaltered, its ligand CXCL10 was found to be upregulated in astrocytes, which remained associated with senile plaques, characteristic of Alzheimer’s disease." (PMID 35794867, 2022). "In the DisGeNET database, LRP6, F11, CXCL10, TCF4 and IGF2 are identified as the top five genes associated with Alzheimer's disease, with association scores of 0.989, 0.981, 0.953, 0.938 and 0.914, respectively." (PMID 38350848, 2024). "Cerebrospinal fluid of patients with mild Alzheimer’s disease shows higher levels of CXCL10 than healthy individuals, which indicates a role of this molecule at the onset of the disease when there is prominent inflammation." (PMID 35794867, 2022). "CXCL10 is also reported to be involved in the pathogenesis of Alzheimer’s disease and cerebral ischemia, and astrocyte-derived CXCL10 is reported to suppress oligodendrocyte progenitor cell differentiation." (PMID 35232977, 2022). "CXCR3 is constitutively expressed on neurons and neuronal processes, along with markedly elevated CXCL10 in astrocytes in the brains of people with Alzheimer’s disease." (PMID 34835465, 2021). "Studying prefrontal cortex samples, we found higher CXCL10 protein levels in those with Alzheimer's disease, compared with aged controls." (PMID 29223680, 2018). "Moreover, Cxcl10 overexpression has been detected in neurodegenerative disorders such as Alzheimer’s disease and Parkinson’s disease." (PMID 40019557, 2025). "The chemokine CXCL10 also known as interferon-γ inducible protein-10 (IP-10) is constitutively expressed in astrocytes, microglia, and neurons and markedly increased in reactive astrocytes in CNS disorders such as Alzheimer’s disease (AD)." (PMID 34692564, 2021). "CXCL10 also mediated an in vitro hippocampal astrocyte migration in Alzheimer’s disease." (PMID 30686982, 2018). "Finally, we investigated CXCL10 within brain samples obtained from deceased individuals with pathological signs of intermediate Alzheimer's disease (AD) and compared them to aged controls." (PMID 29223680, 2018). "It has also been shown that CXCL9 and CXCL10 can induce ERK1/2 activation in mouse cortical neurons, which may promote their survival, but has also been associated with neuronal cell death in models of epilepsy, ischemia, and Alzheimer’s disease." (PMID 24924222, 2014).